CAV1 (caveolin 1)
Diseases named in the same sentence as CAV1 in open-access papers (continued):
Sharing a sentence is not in itself a finding about the gene and the disease.
lung carcinoma (continued). "Interestingly, we were also able to stain caveolin-1 in human adenocarcinoma, and human squamous cell carcinoma, and 14 samples showed caveolin-1 positive staining The results showed heterogeneous staining of CAV-1 was observed in lung cancer patients." (PMID 34762666, 2021). "For example, multiple genes in the AT1 cell program were closely related to pulmonary veno-occlusive disease (PVOD) (Bmpr2 and Eif2ak4), lung cancer (Itga9 and Braf), pulmonary fibrosis (Cadm1 and Itgb6), pulmonary hypertension (Bmpr2 and Cav1), and pulmonary emphysema (Itgb6)." (PMID 34873160, 2021). "Interestingly, the data have shown several fold upregulation of DNA repair genes like RAD51b, RAD 18 and SOX2 cancer stem cell markers, MUC5AC and TGFBR2 in radiation resistant and caveolin-1, overexpressed A549 lung cancer cells." (PMID 34762666, 2021). "In addition, the natural compound chrysotobibenzyl was shown to suppress integrins β1, β3, and αv via a Cav-1-dependent mechanism and to inhibit lung cancer cell migration." (PMID 33920031, 2021). "Cav-1 can also facilitate lung cancer cell proliferation via other pathways." (PMID 31991790, 2020). "Due to these functions, Cav-1 can be considered to act as a target for lung cancer therapy." (PMID 31991790, 2020). "In addition to this, multiple bioactive molecules have been confirmed to target Cav-1 to carry on their anti-tumor functions in lung cancers." (PMID 31991790, 2020). "The context-dependent role of Cav-1 is seen also in lung cancer." (PMID 31991790, 2020). "In lung cancer, the regulatory functions of Cav-1 on cell apoptosis are controversial." (PMID 31991790, 2020). "In lung cancer, Cav-1 is found to act on multiple downstream effectors, such as epidermal growth factor receptor (EGFR), extracellular regulated protein kinases (ERK), focal adhesion kinase (FAK) and protein kinase B (AKT), to mediate key aspects of cancer progression." (PMID 31991790, 2020). "More importantly, mRNA expression of both Cav-1 and Sirt-1 significantly (p < 0.05) decreased concomitantly with miR204-5p upregulation implying that elevated miR204-5p RNA is associated with TL-induced cytotoxicity in A549 and NCI-H460 lung cancer cells." (PMID 32733649, 2020). "When comparing lung cancer tissues with their adjacent normal tissues, the expression of lnc-BMP1-1 were decreased, especially in patients with cigarette smoking history (P=0.027), and positively associated with the expression of Cav-1 (P<0.001)." (PMID 31901898, 2020). "Furthermore, CAV1 has been shown to control proliferation and apoptosis of human lung carcinoma cell lines." (PMID 32458269, 2020). "Based on the origin of lnc-BMP1-1 and the potential function of Cav-1 in conjunction with oxidative stress induced by cigarette smoke, we hypothesized that the decreased expression of lnc-BMP1-1 may reduce the expression of Cav-1 and lead to lung cancer." (PMID 31901898, 2020). "The expression of Cav-1 and clinical characteristics of lung cancer patients." (PMID 31901898, 2020). "Cav-1 can also be a predictor for lung cancer patients’ prognosis." (PMID 31991790, 2020). "Similarly, determined by immunoprecipitation, western blot and immunofluorescence, NO can trigger S-nitrosylation of Cav-1 and induce anoikis resistance in lung cancer." (PMID 31991790, 2020). "Cav-1 can also function to inhibit lung cancer cell migration." (PMID 31991790, 2020). "A high Cav-1 level could contribute to the entry of albumin and nab-paclitaxel (albumin-bound paclitaxel) into H23 lung cancer cells, therefore, enhancing cell apoptosis; while drug resistance is shown in these cells following Cav-1 reduction." (PMID 31991790, 2020).
lung carcinoma (continued). "Cav-1 attenuates hydrogen peroxide-induced oxidative damage to lung carcinoma cells." (PMID 31901898, 2020). "We identified at least five proteins of interest (NKX2-1, CAV1, YBX1, FN1 and CDH3) with two different machine learning models that may be associated with lung cancer patient survival." (PMID 33086649, 2020). "In lung cancer, Cav‐1 plays both suppressive and promoting roles." (PMID 32508059, 2020). "Cav-1 knockdown in lung cancer cell lines reduced cell migration in vitro." (PMID 31297035, 2019). "Research showed that CAV1 can mediate lung cancer cells apoptosis through STAT3 pathway." (PMID 31296840, 2019). "In lung cancer, contradictory roles of Cav-1 have been reported." (PMID 31297035, 2019). "To date, few studies have reported that BM is correlated with Cav-1 expression in lung cancer." (PMID 31297035, 2019). "In our study, CAV1 may be considered to play a positive role in the genesis and development of lung cancer." (PMID 29190968, 2017). "Thus, our results add to the notion that STAT3 activation by Cav-1 is required for lung cancer electrotaxis." (PMID 29221162, 2017). "Finally, we evaluated the relationship between expression level of CAV1 and prognosis of lung cancer." (PMID 29190968, 2017). "In the present study, we performed a case-control study to assess the relationship between SNPs in CAV1 and the risk or survival of lung cancer in Chinese female non-smokers." (PMID 29190968, 2017). "Given the importance of Cav-1 in cancer invasion and the observation that Cav-1 expression was much higher in H1650-M3 cells than was seen in H1650 cells, we next investigated whether Cav-1 was involved in electrotaxis of lung cancer cells." (PMID 29221162, 2017). "They found that overexpression of Cav-1 generated significantly higher superoxide anion level and could sensitize cisplatin-induced lung carcinoma cell apoptosis." (PMID 28546853, 2017). "CAV1 plays a negatively regulatory role in lung cancer development." (PMID 29097801, 2017). "Interestingly, Cav-1high expression also indicates an improved progression-free survival (PFS) and postprogression survival (PPS), further indicating the tumor suppressive role of Cav-1 in lung cancer." (PMID 28546853, 2017). "To address whether Cav‐1 is necessary for premature senescence, we first monitored cellular proliferation by counting cell numbers and using a colony‐forming assay after Cav‐1 knockdown in A549 human lung carcinoma cells, which highly express Cav‐1." (PMID 28514055, 2017). "In particular, our analysis also revealed a close link between Cav-1 and lung cancer." (PMID 28546853, 2017). "Thus, our results, together with those findings, indicate that Cav-1 signaling mediates electrotaxis of lung cancer cells." (PMID 29221162, 2017). "Taken together, these results suggest that endogenous EFs in the tumor micro-environment might play an important role in lung cancer metastasis by guiding cell migration through a Cav-1/STAT3-mediated signaling pathway." (PMID 29221162, 2017). "For example, Cav-1 could attenuate hydrogen peroxide-induced oxidative damages to lung carcinoma cells." (PMID 28546853, 2017). "In summary, the K176R mutant of CAV1 reduced the interaction between CAV1 and P-glycoprotein as well as the retention of doxorubicin in lung cancer cells, which could potentially transform cancer cells into MDR cells." (PMID 26843476, 2016). "Cav1 up-regulation enhanced cell mobility/migration, increased directional motility and invasion in vitro in Ewing's sarcoma tumors, hepatocellular tumors, lung carcinoma or even HNSCC." (PMID 26474461, 2015). "Moreover, Cav-1 was shown to facilitate metastasis and induce anoikis resistance in lung carcinoma cell lines." (PMID 24967418, 2014). "Therefore, we aimed to investigate the possible impact of the Cav-1 protein on lamellipodia formation and cancer cell motility in human lung cancer cells." (PMID 24955034, 2014).
lung carcinoma (continued). "Following the statistical analysis of Cav-1 immunostaining and the clinical data of several primary lung cancer cohorts, the expression of Cav-1 was demonstrated to statistically correlate with poor differentiation, pathological stage and lymph node metastasis, as well as a predicted poor prognosis." (PMID 25202343, 2014). "In addition, Cav-1 levels and the migratory action of other lung cancer cells, namely, H460 and A549, were assessed, and the migration of these cells was found to be correlated with the basal Cav-1 level." (PMID 24955034, 2014). "Recently, we have provided the data indicating that Cav-1 in the detached lung cancer cells could inhibit anoikis process of the cells by sustaining the antiapoptotic Mcl-1 protein." (PMID 24967418, 2014). "In addition to the regulatory role of ROS in Cav-1 expression, the feedback antioxidant function of Cav-1 was reported in human lung cancer cells." (PMID 24939878, 2014). "Although roles of Cav-1 on lung cancer cell behaviors have been intensively explored, the role of such a protein on lung cancer cell adhesion to endothelium surface is largely unknown." (PMID 23460862, 2013). "Together with the fact that Cav-1 expression in lung cancer was shown to relate to poor prognosis, and most of the cancer-related death in this cancer was shown to link with metastasis, it is of great interest to investigate the entire regulatory role of this protein on cancer metastasis." (PMID 23460862, 2013). "Although some studies suggested that Cav-1 may play a role in inhibiting cancer progression in certain cancers, in lung cancer, Cav-1 potentiates cancer aggressiveness as well as metastasis." (PMID 23460862, 2013). "In the deterioration and progression of lung cancer, cav-1 can be up-regulated, which may contribute to tumor invasion and metastasis." (PMID 22200856, 2012). "In primary lung cancer, only a few studies on cav-1 expression have been reported." (PMID 22200856, 2012). "All these findings contribute to explaining the crucial role of stromal Cav1 as a regulator of cytokine production and inflammation and their harmful consequences on the poor clinical outcome observed in patients with decreased Cav1 expression in breast, ovarian and lung cancer." (PMID 36430209, 2022). "In addition, Cav-1 was demonstrated to positively regulate anoikis resistance in lung cancer cells." (PMID 33920031, 2021). "Thus, TCGA data showed that modified CAV1 induced worst prognosis in lung cancer patients." (PMID 34762666, 2021). "Moreover, we have also discovered caveolin-1 as a potential clinical biomarker for lung cancer which could be used in clinical setting to monitor patient’s response to radiation therapy and recurrence." (PMID 34762666, 2021). "Thus, the data demonstrated that caveolin-1 could be used as a blood biomarker for radio-resistance, and tumor progression in lung cancer patients." (PMID 34762666, 2021). "In order to examine the clinical potential of caveolin-1 as a liquid based biomarker for radio-resistance in lung cancer, we have made an attempt to demonstrate that caveolin-1 could be used as liquid based biomarker to predict radio-resistance in cancer patients." (PMID 34762666, 2021). "Therefore, it is necessary to decipher the detailed correlation between Cav-1 and lung cancer." (PMID 31991790, 2020). "Interestingly, a relation between Cav-1 and NO has emerged in the context of anoikis - i.e., the detachment-induced apoptosis—in lung cancer cells, where it has been demonstrated that Cav-1 is rapidly ubiquitinated and degraded by the proteasome after cell detachment and anoikis." (PMID 30155439, 2018). "Moreover, Luanpitpong and colleagues have found that superoxide anion and hydrogen peroxide could attenuate the expression of Cav-1 in lung carcinoma H460 cells." (PMID 28546853, 2017). "We also found that CAV1 expression may play a positive role in lung cancer." (PMID 29190968, 2017).
lung carcinoma (continued). "In lung cancer cell lines, there is controversy about whether CAV1 is expressed." (PMID 29190968, 2017). "We found that the CAV1-rs1049337, CAV1-rs926198 may affect the susceptibility of lung cancer in the Chinese female non-smokers." (PMID 29190968, 2017). "Interestingly, a study in A549 lung carcinoma cells showed that MDA-9 might also prevent caveolin-1-mediated internalization of TGFβR1 leading to enhanced canonical TGFβ1 signaling." (PMID 27863394, 2016). "In addition, Cav-1 expression is significantly induced after treating lung cancer cells with etoposide or bleomycin, indicating that Cav-1 might be a stress-related protein." (PMID 26431273, 2015). "Thus, we assessed whether the basal expression level of Cav-1 in human lung cancer cells could affect their migration." (PMID 24955034, 2014). "Furthermore Cav1 and Cav2 are down regulated, according to previously published results showing a tumor suppressor activity of Caveolin-1 and its down-regulation during lung cancer development." (PMID 21205295, 2011). "The expression levels of Cav-1, ROCK1 and Parkin in lung cancer cells treated with cisplatin are increased, and Cav-1 knockdown can inhibit ROCK1, downregulate Parkin related mitophagy." (PMID 41030451, 2025). "Considering that cav 1 prevents hydrogen peroxide-induced oxidative damage to lung carcinoma cells 107, and higher cav 1 expression enhances the sensitivity of A549 cells to the anti-cancer drug doxorubicin 106, it is evident that downregulating CAV1 could be unfavorable for NSCLC." (PMID 37928877, 2023). "The experimental results show that CEP55, NMU, CAV1, TBX3, FBLN1and SYNM have significantly different expression in lung cancer." (PMID 36404510, 2022). "Thus, we conclude that caveolin-1 is involved in radio-resistance and contributes to tumor aggression, and it has potential to be used as prognostic biomarker for radiation treatment response, and tumor progression for precision medicine in lung cancer patients." (PMID 34762666, 2021). "We analyzed the expression of lnc-BMP1-1 and its relationship with clinical characteristics of lung cancer population, then tried to make clear the mechanism of lnc-BMP1-1 regulating Cav-1 through in vitro and in vivo experiments." (PMID 31901898, 2020). "Taken together, results from these inhibitor studies suggest SIRT-1 and SIRT-3 play important roles in mediating TL-induced down-regulation of CAV-1 protein expression in A549 and NCI-H460 lung cancer cells." (PMID 32733649, 2020). "Hence, Cav-1 may play a significant role in lung cancer cell migration." (PMID 31991790, 2020). "In A549 cells, Cav-1 and protein arginine methyltransferase 5 (PRMT5) can synergistically facilitate the exteriorization of Eno-1, a glycolytic enzyme that can promote lung cancer cell migration." (PMID 31991790, 2020). "Down-regulation of caveolin-1, Mcl-1 and Bcl-2 as well as suppression on AKT and ERK activation successfully initiate detachment-induced cell death in anoikis-resistant lung cancer cells." (PMID 29631569, 2018). "The aim of this study was to investigate the clinicopathological significance and prognostic value of stromal CAV1 and CAV2 expression in lung cancer." (PMID 29850392, 2018). "To explore the relationship between stromal CAV1 and CAV2 expression and lung cancer, we analyzed expression for both proteins in stromal cells of the primary tumor as well as lymph nodes of human lung cancer tissues placed on TMAs." (PMID 29850392, 2018).
lung carcinoma (continued). "Moscatilin, a dibenzyl derivative present in orchid sensitizing anoikis in human lung cancer cells by decreasing the level of Akt and ERK, expression of caveolin 1 and anti apoptotic MCl-1 protein." (PMID 28223935, 2017). "Among these, CAV1 and JNK (MAPK8) were identified as central hubs of the apoptosis-related interactome network in the cordycepin-treated lung cancer cells." (PMID 28099944, 2017). "We attempted to identify the pathway by which cordycepin promotes CAV1-mediated JNK/Foxo3a signaling, thereby inducing apoptosis in human lung-cancer cells." (PMID 28099944, 2017). "Cav‐1 knockdown‐induced senescence was explored in HCT116 human colorectal carcinoma cells, human diploid fibroblasts (HDFs), and H460 human lung cancer cells with similar results." (PMID 28514055, 2017). "Finally, we found that CAV1 expression may play a positive role in lung cancer." (PMID 29190968, 2017). "Noncytotoxic doses of NO enhanced anoikis resistance and migration in lung cancer H23 cells via an increase in lamellipodia, epithelial-mesenchymal transition (EMT) markers including vimentin and snail, and caveolin-1 (Cav-1)." (PMID 24967418, 2014). "The relative mRNA level of the cav-1 gene (cav-1 per GAPDH, mean ± SD) showed significant differences between lung cancer tissue (1.146±0.167) and the surrounding normal lung tissue (3.254±0.248)." (PMID 22200856, 2012). "The best three single gene discriminators are CAV1, SFTPC and VWF for lung cancer, having the same classification accuracy, 99.1% on the training set and 98.2% and 100%, 96.3% and 82.5%, and 88.9% and 100% on the two test sets, respectively." (PMID 21060876, 2010). "In this article, we mainly discuss the structure of Cav-1 and its critical roles in lung diseases, such as pneumonia, acute lung injury (ALI), asthma, chronic obstructive pulmonary disease (COPD), pulmonary hypertension, pulmonary fibrosis, and lung cancer." (PMID 39380904, 2024). "Interestingly, the TCGA data on lung cancer patients also supported our hypothesis that CAV1 gene deletion causes loss of functional caveolin-1 protein which is involved in cancer aggression and chemo and radio-resistance, and caveolin-1 loss has also been linked to cancer aggression." (PMID 34762666, 2021). "Even though this might have been proven to be true in breast and lung cancer, our results seem to suggest that in PDAC patients, high levels of expression of Cav-1 might have a completely opposite effect." (PMID 34590611, 2021). "As reported for the rat DLC1 homolog, immunoprecipitation studies confirmed complex formation between PLCD1 and DLC1 in H1703 cells, a human lung cancer cell line that expresses readily detectable levels of both proteins, as well as between PLCD1 and Caveolin-1." (PMID 34727930, 2021). "Nonetheless, these inhibitor studies indicate that SIRT-1 and SIRT-3 play pivotal roles in mediating TL-induced down-regulation of CAV-1 protein expression in A549 and NCI-H460 lung cancer cells, further supporting the importance of SIRT-3 in TL-mediated cytotoxicity." (PMID 32733649, 2020). "Because of the growth inhibition and associated apoptotic effects of TL in a wide variety of epithelial and hematological cancer cell lines, including NSCLC cells, we investigated the potential changes in CAV-1 mRNA/protein expression following TL treatment in A549 and NCI-H460 lung cancer cells." (PMID 32733649, 2020). "We have proven that the expression of both lnc-BMP1-1 and Cav-1 could be reduced by CSE, further supporting our hypothesis that lnc-BMP1-1 is involved in the pathway of cigarette smoking-induced lung cancer." (PMID 31901898, 2020). "Then, we hypothesized that LINC81507 can increase CAV1 via sequestering miR-199b-5p, and thereby inhibiting the STAT3 pathway and EMT in lung cancer cells." (PMID 31296840, 2019). "In non-SQC, tumor cells showed low Cav-1 expression in both primary lung cancer and BM (cases with high Cav-1 expression, 33% vs. 27%, respectively, P = 0.368)." (PMID 31297035, 2019).